CD44 (CD44 molecule (IN blood group))
Diseases named in the same sentence as CD44 in open-access papers (continued):
Sharing a sentence is not in itself a finding about the gene and the disease.
tumor (continued). "At the same time, it is a marker for the identification of cancer stem cells (CSCs), as CD44 increases tumor development and progression." (PMID 35884975, 2022). "CS has a strong affinity for the CD44 receptor (high expression of CD44 in the cancer cells), it can accurately target the tumor site." (PMID 35501796, 2022). "The targeted interaction with CD44 on the surface of tumor cells makes HA an ideal drug carrier in cancer treatment." (PMID 35860333, 2022). "A molecular profiling study of CD44 and ALDH expressing endometrial tumor circulating cells found increased expression of NF-κB member RelA associated with tumor infiltration and EMT." (PMID 35328833, 2022). "In our recent study, we found that ALDH+CD44+ cells isolated from ascites-derived tumor cells show enhanced CSC properties." (PMID 35155224, 2022). "The design of these nanosystems is based on the use of HA as the ligand for selective delivery of therapy on tumor cells overexpressing CD44." (PMID 35456622, 2022). "The homodimerization of CD44 plays a key role in an intercellular-to-extracellular signal transduction and tumor progression." (PMID 35733341, 2022). "The distribution of the PDPN-positive cell region was more localized to the peripheral area of the tumor nests than that of CD44- and P63-positive cell regions." (PMID 35159384, 2022). "First, an overall evaluation of CD44 expression in a variety of common tumours was made by using the TIMER and GEPIA2 online databases." (PMID 36316684, 2022). "CD44 molecules are present on tumor cell membranes and can be bound by P-selectin carried on platelet membranes." (PMID 36276645, 2022). "We show that Pin1 plays a central role in promoting the tumorigenic potential of CD44+CD133+ tumor-initiating Caco-2 cells." (PMID 35433695, 2022). "The sensitivity of HCT116‐CSCs to oxaliplatin was tested, and xenograft tumor growth assay was performed to examine the role of CD44 in HCT116‐CSCs tumorigenesis in vivo." (PMID 35229451, 2022). "Using the Kaplan–Meier plotter bioinformatics tool, we identified higher expression levels of the KRAS, MMP7, and CD44 oncogenes in tumor and metastatic samples, compared to adjacent normal tissues." (PMID 35203586, 2022). "This dual tumor acidity and CD44 targeting not only benefits PPTT, but also chemotherapy that requires intracellular uptake of chemotherapeutic agents." (PMID 35621478, 2022). "Further staining of tumor slices with CD44 and PD-L1 showed that CpG+OVA+PTX+CQ-N/A emitted stronger fluorescence than the free DiD solution, consistent with the in vivo imaging results." (PMID 36303207, 2022). "The identification of CD44 as a negative regulator of in-cell killing on tumor cells provides an ideal target for therapeutic intervention." (PMID 35436988, 2022). "By implanting human BC cells in immunocompromised mice, it was noted that the ability to form new tumours was constrained to a subgroup of BC cells that uniquely expressed the surface makers CD44+/CD24−." (PMID 36077812, 2022). "The binding of HA derived from CAMs to CD44 expressed on OC plays a significant part in promoting tumor metastasis and chemoresistance." (PMID 36268019, 2022). "Patients that were AJCC stage III had high CD44 expression (P=0.036) as well as those with tumour size T3 (P=0.007)." (PMID 35296132, 2022). "This study reveals that PIP2 promotes the dimerization of CD44 under different palmitoylation states, which is favorable for tumor cell metastasis." (PMID 35733341, 2022). "The results showed that expression of CD44 was upregulated in ccRCC tumor tissues compared with normal tissues." (PMID 35024436, 2022).
tumor (continued). "In the immunohistochemical staining of lung SCC tissue, PDPN is mainly localized at the periphery of invading tumor nests with CD44 and P63." (PMID 35159384, 2022). "The tumor invasiveness promoted by MMP-9 seems to be mediated by the binding of the proteolytically active metalloprotease to the CD44 ectodomain." (PMID 35785191, 2022). "It was found that CD44 expression worsens the prognosis due to increased tumour aggressiveness and high resistance to chemotherapy and radiotherapy." (PMID 36415383, 2022). "CD44 is one major determinant of adhesion and pulmonary metastasis of such tumor cells and binds E-selectin most likely through β-1,6-GlcNAc-branched N-glycans elongated with poly-LacNAc." (PMID 35031433, 2022). "Previous publications have reported contradicting results—both upregulation and/or downregulation of MUC1, CD44, and HA have been connected to tumor progression." (PMID 36359337, 2022). "The results acquired showed that increased expression levels of KRAS, MMP7, and CD44 promoted primary tumor and metastasis in CRC samples compared to adjacent normal samples." (PMID 35203586, 2022). "One of the therapeutic approaches to treat overexpressed CD44 tumor cells can be the downregulation of CD44 molecule by targeting with antisense vector or monoclonal antibodies." (PMID 36185622, 2022). "CD44 is expressed on tumor cell surfaces and combines with ligands, activating corresponding signals and participating in tumor cell proliferation, motility, survival, chemical resistance, and invasion." (PMID 35754803, 2022). "In HCC xenograft model, CD44-Apt1 efficiently homed to tumor xenografts in a CD44 expression-dependent manner." (PMID 34976591, 2022). "CAM MCF10CA tumor paraffin sections were double stained with CD44 antibody and HABC for a more detailed analysis by confocal microscopy." (PMID 35574334, 2022). "We performed immunohistochemical analysis on tumor samples, for relevant gene-expression-based markers for basal type (CD44, CK5/6) and luminal type (CK20 and pPARγ)." (PMID 35805028, 2022). "Further study showed that CD44+ GCSCs isolated from tumor tissues were significantly enriched after treatment with 5-FU." (PMID 36176765, 2022). "We applied the TNM plot analysis to compare expressions of the KRAS, MMP7, and CD44 genes in normal, tumor, and metastatic CRC samples from RNA-Seq data." (PMID 35203586, 2022). "Among them, CD44, a transmembrane adhesion glycoprotein, has been commonly used to target receptors for targeted tumor treatment." (PMID 36096856, 2022). "In the case of papillary RCC, MMP-2 expression was positively correlated with patient age (p < 0.05), while CD44 expression was positively correlated with tumor stage (τ = 0.26, p < 0.05)." (PMID 36079127, 2022). "Elevated OPN engages CD44 to suppress T cell activation and promote tumor cell stemness to advance cancer." (PMID 36078039, 2022). "Some types of tumor cells overexpress CD44 on their surface that facilitates targeting them by increasing the concentration of NPs in the tumor tissues." (PMID 35157166, 2022). "In PC sections, 46% (± 15%) of cancer cells were CD44-positive, indicating that nearly half of all PC tumor cells expressed this stem cell marker." (PMID 35844581, 2022). "Majority of tumor specimens showing CD44 expression were collected from oral cavity and relatively smaller numbers were collected from other sites like larynx (n = 6), pharynx (n = 7), and nasal cavity (n = 3) (Suppl 2)." (PMID 35274800, 2022). "CD44 expression at the tumor-cell surface has been shown to interact with hyaluronan in the microenvironment, thereby activating signaling pathways that induce migration, invasion and metastasis, while RHAMM acts on the intracellular HA concentration." (PMID 36428513, 2022). "Ki-67 is the main marker of cell proliferation in clinicopathology, while CD44 is an important marker of tumor invasion and metastasis." (PMID 36082168, 2022).
tumor (continued). "Regarding the analyzed patient samples, more than half of tumor cells acquired stem cell-like features with markers such as CD44, CD133, and Lgr5." (PMID 35844581, 2022). "In the case of human colon cancer, the tumor-forming subsets in a patient's tumor were defined using CD44, epithelial cell adhesion molecule (EpCAM also known as an epithelial-specific antigen or ESA), and CD166." (PMID 35800881, 2022). "Many studies have reported that CD44 is aberrantly expressed in several human tumors, and it plays a crucial role in cancer metastasis and tumor growth 35-40." (PMID 36439876, 2022). "Tumors were divided in two groups according to median of ESA+CD24+CD44+ or CXCR4+CD133+ cell percentage [high stemness tumor (HST) > median, low stemness tumor (LST) ≤ median]." (PMID 36142575, 2022). "CD44 highly expressed tumor cells including Huh-7 cells, SK-OV-3 cells, and MDA-MB-231 cells were used to evaluate the tumor affinity of the PM biomimetic lipid vesicle (PL)." (PMID 36559108, 2022). "CD44 is verified as a cell-surface biomarker of cancer stem cells (CSCs) and served as a crucial regulator for tumor development." (PMID 36217151, 2022). "This was also noted by Krump and Ehrmann who found a total of 62% positive specimens and significantly increased CD44 expression in the floor of the mouth tumours as compared to the tongue." (PMID 35296132, 2022). "P-selectin on the surface of platelets works in conjunction with CD44 on the surface of 4T1 tumor cells to increase the uptake of nanoparticles and promote the accumulation of nanoparticles in metastatic tumors." (PMID 36276645, 2022). "The results demonstrated increased therapeutic efficiency in mammary tumor spheroids model as nanoparticles delivered to tumor microenvironment specifically targeted CD44 overexpressing CSCs due to the high affinity between CD44 receptors and chitosan." (PMID 35456698, 2022). "Although CD44 levels correlated with poor prognosis, in comparison with adjacent normal tissues, its expression level was decreased in tumor tissues." (PMID 36292918, 2022). "HA binding of CD44 results in stimulation of downstream cascade of pathways, activation of growth pathways, and under expression of tumor suppressor mechanism." (PMID 36185622, 2022). "Specifically, CD44 was co-immunoprecipitated with Eno1 and the silencing of CD44 suppressed Eno1's anti-tumor action." (PMID 35547745, 2022). "In regard to the overexpressed CD44 in both MSCs and tumor cells, MSCs are supposed to load more nanoparticles with HA coating through receptor-mediated endocytosis." (PMID 35458619, 2022). "CD44 was found to be widely expressed in stem cells, monocytes, tumor cells, and vascular endothelial cells (ECs), and it participates in the pathological process under ischemic conditions." (PMID 36463112, 2022). "Well-characterized stem cell markers CD44 and CD24 have been linked to younger age at diagnosis, higher odds of unfavorable tumor characteristics, including triple-negative status and distant metastasis." (PMID 36590957, 2022). "Studies have found that the CSCs of TNBC exhibit higher CD44 and PD‐L1 expression than differentiated tumor cells." (PMID 36089659, 2022). "The simplest explanation would be that the even though drastically reduced, MMP9 levels in CD44-/- GAMs are still sufficient to promote tumor invasion." (PMID 35992852, 2022). "In fact, the CD44+CD24+EpCAM+ phenotype was reported to exhibit a 100-fold increase in the tumor-initiating capacity versus the other cancer cells, both in vitro and in vivo." (PMID 36142575, 2022). "In the case of CD44-positive IF group, we observed the deconvolution result for each IF group and found out some sites were mainly composed of tumour cells and some other sites were composed of endothelial, fibroblast, and CD4 + T cells." (PMID 35534484, 2022). "Both markers co-localized with CD44 and were most highly expressed in the basal layers of the tumours." (PMID 35768510, 2022).
tumor (continued). "Further examination of the ARCaPM-IR model demonstrated several similarities to other radiation-resistant tumor cell types such as mesenchymal morphology and elevated cell surface CD44 expression." (PMID 35626095, 2022). "HA promotes these characteristics and regulates associated behaviors, such as cell adhesion, motility, and growth in BC, through its interactions with the cell–surface glycoprotein CD44, which is widely expressed in BC tumor cells." (PMID 36230537, 2022). "Another study used polymer micelles coupled with miR-205 and gemcitabine to target markers such as OCT3/4, CD44, and Tubulin 3, showing a substantial reduction in tumor volume, implying that pancreatic cancer cells’ sensitivity to gemcitabine was restored." (PMID 35456698, 2022). "By regulating P- and L-selectin activity, CD44 is thought to be involved in hematogenous dissemination, including leukocyte recruitment and metastatic tumor spread." (PMID 36013184, 2022). "CD44 labeling of equine HNSCC sections revealed the presence of CD44+ tumor cells in 100% of tumors analyzed, with positive tumor cells ranging between >10 and >50%." (PMID 35215208, 2022). "Targeted delivery due to the HA/CD44 interaction is an advanced option for promoting tumor drug delivery." (PMID 35456670, 2022). "Immunofluorescence microscopy showed that groups of CD44-positive pNET cells were adjacent to vascular networks within the tumor microenvironment." (PMID 36497140, 2022). "Comparing CD166 vs CD133 vs CD44 expression patterns with the tumor grading, we observed the lowest levels of all three markers in normal tissue, grade G3, similarly in the case of CD166 and CD133 tumor tissue." (PMID 36291969, 2022). "The differences in levels of seven EMT-associated markers, Ki-67, DAXX, CD24, CD44, vimentin, laminin and PDX1 plus CgA and NSE (neuroendocrine markers) enabled a distinct molecular signature for each tumour grade to be generated." (PMID 36362433, 2022). "In the present study, we examined gene expression of CD44 in the tumor tissues of GBM to identify the features of specific phenotypes of GBM." (PMID 35624954, 2022). "Very interesting was the finding that knockdown of catulin results in the significant attenuation of CD44 signal on the membrane, when analyzing cells on flow cytometry and in tumor tissue from xenograft transplant." (PMID 35879327, 2022). "We reported that the values of the ratio of CD44 expression in the tumor periphery to CD44 expression in the core (P/C ratio) correlated well with the GBM phenotypes on MRI and the prognosis of patients with GBM." (PMID 35624954, 2022). "In some cases, CD44+CD271+ cells were predominantly detected within tumor margins representing infiltrative tumor fronts." (PMID 35215208, 2022). "When comparing normal vs tumor among each marker, a similarity was noted with the lowest level of CD44 expression at T1, highest at T2, and T4 was higher than T3." (PMID 36291969, 2022). "Approximately 1 × 105 CD44+CD133+ tumor-initiating Caco-2 cells were suspended in 100 μl of injection solution and inoculated subcutaneously in the flanks of NSG mice." (PMID 35433695, 2022). "Another similarity was noticed when comparing the expression of CD133 and CD44 in tumor tissue, with the highest levels related to the N0 stage, which decreased in the N1 stage and increased in the N2 stage." (PMID 36291969, 2022). "The population of CD44+ OC cells possesses self-renewal, tumor-initiating and sphere-forming capacities." (PMID 36612107, 2022). "The synthesized HA-mPEG-Cis NPs can target CD44-positive CRC cells responsive to the weakly acidic tumor environment." (PMID 36033392, 2022). "The results indicated that CD44 overexpressed on the surface of both MSCs and tumor cells not only improved PTX/HA-PLGA micelle loading in MSCs, but also promoted the drug transfer between MSCs and adjacent cancer cells." (PMID 35458619, 2022).
tumor (continued). "Curiously, CD44 expression was also higher in patients that had floor of the mouth (71%) as a secondary site of tumour (P=0.038)." (PMID 35296132, 2022). "When TMZ was added to the tumor cells there was an up-regulation of CD44, CD54 and MHC I expression in NK supernatant-treated GS025 and NCH421k cells as compared to only NK supernatant- and only TMZ-treated cells." (PMID 35538218, 2022). "Meanwhile, serum exosomal CD44 was detected and compared in the prior different groups of tumor-bearing mice." (PMID 35359362, 2022). "Hyaluronans are the major ligands of CD44, but some isoforms bind to additional ligands modulating angiogenesis, tumor growth, and invasion." (PMID 35456655, 2022). "We also show that Juglone and KPT6566 suppress CRC cell growth and colony formation and inhibit the tumorigenic properties of CD44+CD133+ tumor-initiating Caco-2 cells." (PMID 35433695, 2022). "In cancer biology, CD44 shows a significant positive correlation with tumour recurrence, mortality, metastasis and invasion in malignant cancers." (PMID 35090088, 2022). "Adipose-derived stem cell secretome promoted the proliferation apoptosis and increased CD44+ CD24− tumor-initiating cells in MCF-7 and MDA-MB-231 cells." (PMID 36550571, 2022). "GSCs isolated from human LN18 cells with cell surface vimentin overexpression have been found to present 95% CD133 expression and 98% CD44 expression, suggesting that GSCs that express surface vimentin possess tumor-initiating properties." (PMID 36362359, 2022). "It is noteworthy that CD44 expression was found upregulated in different tumours, promoting cancer cell invasion and migration." (PMID 35264209, 2022). "These antibodies can be conjugated with anti-tumor drugs to target cells overexpressing CD44 to favor the antitumoral drug uptake or act as blockers of CD44-mediated signalling." (PMID 35785191, 2022). "The HA was coupled to nanoparticles for targeting CD44-positive CSCs and can be degraded under the action of HA enzyme in tumor cells, thereby promoting the release of load." (PMID 36182897, 2022). "Another member of this immunoglobulin superfamily, namely CD44, was also upregulated by Fra-2 as well in the scid mouse xenograft tumours and metastasized cells in the lungs as confirmed by Western blot and immunohistochemistry." (PMID 34693476, 2022). "Several studies indicated the role of CD44 isoform in tumor invasion and metastasis with poor survival outcome." (PMID 35566360, 2022). "(II) The presence of HA in CAT@HA-HMME NPs is specifically accumulated within cancer cells via CD44-HA recognition, resulting in high retentions in the tumor site." (PMID 35387175, 2022). "The CD44/OPN interaction supports tumor progression through the activation of the phosphatidylinositol 3-kinase/Akt signaling pathway, increasing consequently cell survival." (PMID 35785191, 2022). "Aberrant upregulation of CD44 in tumor cells is closely related to tumor immune escape and invasion, and involves reduced oxygen levels and regulation of HIF-1 signaling." (PMID 36419877, 2022). "The staining with anti-CD44 antibody was stronger in the miBx tumor sections than in those of miPa and miPk tumors while the staining was almost equivalent in the sections of miPk tumors and miPSCs teratoma." (PMID 35063003, 2022). "CD44, as a mesenchymal marker and a multifunctional cell surface glycoprotein, plays a critical role in tumor progression and specifically in collective invasion in luminal-like BrCa." (PMID 35680853, 2022). "We found that PTS, used alone or in combination with cisplatin, substantially suppressed TGF-β and CD44 expression, thereby reducing the metastatic potential of the tumor cells." (PMID 36077992, 2022). "To investigate the impact of CD44 in the TME on tumor invasion we used the approach of organotypic brain slices." (PMID 35992852, 2022). "As a protein intervened in cell motility, CD44 has been utilized as a marker for tumor aggressiveness." (PMID 36079127, 2022).